ACKR1 (atypical chemokine receptor 1 (Duffy blood group))
Diseases named in the same sentence as ACKR1 in open-access papers (continued):
Sharing a sentence is not in itself a finding about the gene and the disease.
G6PD deficiency (2 papers, 2017 to 2018). An X-linked genetic condition caused by alterations in the gene G6PD that result in moderately to severely decreased activity levels of the enzyme glucose-6-phosphate dehydrogenase. "The three traits that have been clearly shown by functional studies to protect against P. vivax are: Duffy negativity (ACKR1 gene), Ovalocytosis (in South East Asian groups) and G6PD deficiency." (PMID 28469196, 2017).
multiple sclerosis (2 papers, 2013 to 2021). A progressive autoimmune disorder affecting the central nervous system resulting in demyelination. "Similar to mast cell numbers, ACKR1 protein expression is increased in chronic inflammatory settings, as indicated by its upregulation on ECs in CNS microvessels during experimental and human multiple sclerosis." (PMID 34033752, 2021).
non-small cell lung carcinoma (2 papers, 2012 to 2020). A group of at least three distinct histological types of lung cancer, including non-small cell squamous cell carcinoma, adenocarcinoma, and large cell carcinoma. "Moreover, ACKR1 overexpression in different tumor mouse models of non-small cell lung cancer (NSCLC) led to a decrease in tumor cellularity and vascularity, as well as significantly increased necrosis, what inhibited tumorigenesis and reduced the metastatic capacity of tumor." (PMID 32456359, 2020).
periodontitis (2 papers, 2013 to 2025). An acute or chronic inflammatory process that affects the tissues that surround and support the teeth. "In addition, it can act on endothelial cells via the CXCL1/ACKR1 and CXCL13/ACKR1 axes, and we hypothesized that this may promote endothelial cell angiogenesis, leading to gingival bleeding in periodontitis." (PMID 40370461, 2025).
schizophrenia (2 papers, 2022 to 2026). A major psychotic disorder characterized by abnormalities in the perception or expression of reality. "We propose ACKR1 testing as a cost-effective approach for facilitating access to clozapine, the optimal therapy for treatment-resistant schizophrenia." (PMID 42125771, 2026).
alcohol abuse (1 paper, 2022). The use of alcoholic beverages to excess, either on individual occasions ("binge drinking") or as a regular practice. "Immunofluorescence staining showed that ACKR1+ ECs were widely distributed in sinusoids and venules in the ONFH group, making it possible for ACKR1+ ECs to contact MSCs during vascular injury caused by alcohol abuse and other pathogenic factors." (PMID 35388143, 2022).
anaemia (1 paper, 2022). "SLE of AA had higher rates of anaemia, leucopenia, and thrombocytopenia than those of EA; only the difference in leucopenia was explained by ACKR1-CC genotype." (PMID 36376015, 2022).
autoimmune disease (1 paper, 2024). A disorder resulting from loss of function or tissue destruction of an organ or multiple organs, arising from humoral or cellular immune responses of the individual to their own tissue constituents. "In addition to these cytokines, the results of the qPCR array also showed the expression levels of IL-6R, CCL17, and ACKR1, which are related to inflammatory responses or autoimmune diseases." (PMID 39771147, 2024).
crescentic glomerulonephritis (1 paper, 2024). A histopathologic term for a pattern of diseases characterized by extensive crescent formation in the glomeruli; patients present clinically with rapid deterioration of renal function, and possible progression to end-stage renal failure within weeks or months. "In KTx, ACKR1 expression increases during acute rejection and crescentic glomerulonephritis." (PMID 39602449, 2024).
diabetes (1 paper, 2024). "MCP-1, being an overall chemotactic factor, recruits macrophages for immune responses, which along with its receptors (such as CCR2, ACKR1, and ACKR2), significantly impact diseases across different systems like cancer and diabetes." (PMID 39654886, 2024).
gallbladder tumors (1 paper, 2021). "Two distinct endothelial cells (KDR+ and ACKR1+), which were involved in angiogenesis and lymphangiogenesis, showed remarkable ligand–receptor interactions with primary GC cells and macrophages in gallbladder tumors." (PMID 34185421, 2021).
Hashimoto thyroiditis (1 paper, 2023). An autoimmune disorder caused by the production of autoantibodies against thyroid tissue. "In the Hashimoto’s thyroiditis (HT), one study has proved that CCL5/ACKR1 axis facilitated the trans-endothelial migration of lymphocytes." (PMID 37207221, 2023).
leukopenia (1 paper, 2024). "This ethnic leukopenia is due to genetic factors, specifically to alterations in the ACKR1 gene (previously called DARC), which is associated with a decrease in Plasmodium vivax infection but does not lead to a higher frequency of bacterial infections." (PMID 39446793, 2024).
lung carcinoma (1 paper, 2023). "Similarly, another study also identified two types of tumor ECs: INSR+ tumor EC (INSRhiHSPG2+PLVAP+) and ACKR1+ tumor EC (ACKR1+SELP+IL1R1+) in early-stage lung cancer that radiologically manifests as part-solid nodules." (PMID 37187731, 2023).
osteoarthritis (1 paper, 2022). A noninflammatory degenerative joint disease occurring chiefly in older persons, characterized by degeneration of the articular cartilage, hypertrophy of bone at the margins and changes in the synovial membrane. "The role of ACKR1+ ECs in aseptic inflammation and bone remodelling of subchondral bone in osteoarthritis merits further investigation." (PMID 35388143, 2022).
peritonitis (1 paper, 2018). Inflammation of the peritoneum (tissue that lines the abdominal wall and covers most of the organs in the abdomen). "Furthermore, Ackr1−/− chimeras exhibited reduced tissue infiltration of neutrophils in a TNF-driven peritonitis model and in models of cutaneous inflammation as elicited by local injection of TNF or LPS." (PMID 30446388, 2018).
prostate tumors (1 paper, 2025). "To confirm the cell type-specific expression pattern of ACKR1, we analyzed scRNA-seq data from prostate tumors and castrate-resistant prostate cancer (CRPC) needle biopsies." (PMID 41258098, 2025).
rheumatoid arthritis (1 paper, 2023). A chronic, systemic autoimmune disorder characterized by inflammation in the synovial membranes and articular surfaces. "ACKR1 binds chemokines at the inflamed synovial endothelium, and diminished expression of ACKR1 may be associated with rheumatoid arthritis." (PMID 37006247, 2023).
soft tissue sarcoma (1 paper, 2024). A malignant neoplasm arising from muscle tissue, adipose tissue, blood vessels, fibrous tissue, or other supportive tissues excluding the bones. "Compared to non-metastatic patients, the GREM2 and CTSS genes exhibited significantly higher expression levels, while TINAGL1, ACKR1, and HLA-DRB1 showed a tendency to increase in metastatic soft tissue sarcoma (SS); however, these differences were not statistically significant." (PMID 39735532, 2024).
uveitis (1 paper, 2020). An inflammatory process affecting a part of or the entire uvea. "Other genes were already implicated in other inflammatory disease models but not in uveitis, such as Lrg1, Ackr1 and Timp1." (PMID 32183784, 2020).
tumor (80 papers, 2010 to 2026). "Overall, a cancer-protective role for ACKR1 is supported by cell culture, mouse models, and genetic associations, and independent anti-angiogenic properties for endothelial, erythroid, and tumor ACKR1 expression can contribute to improved patient outcomes." (PMID 37006247, 2023). "Another mechanism underlying the antitumor effect of ACKR1 is related to the expression of CD82/KAI1 on tumor cells." (PMID 37108425, 2023). "Endothelial cells characterized by expression of the atypical chemokine receptor ACKR1 were increased after NEC which is noteworthy given their association with prevention of tumor progression in other settings." (PMID 36253784, 2022). "DEG analysis after chemotherapy showed only moderate transitions whilst tumor-associated DEGs included ACKR1, RGCC and TM4SF1." (PMID 36253784, 2022). "Accordingly, ACKR1 was causatively linked to reduced tumor growth and metastasis in animal models, and ACKR1 single nucleotide polymorphisms that were related to chemokine sequestration affected angiogenesis, tumorigenesis and lung metastasis." (PMID 32582148, 2020). "Interestingly, ACKR1’s role in cancer has been reported as dominantly protective against tumor metastasis and uncontrolled proliferation, and is associated with positive outcomes." (PMID 41258098, 2025). "Clustering of the projected dataset with the HLCA reference showed that cells expressing the suggested tumor-associated marker ACKR1 were also abundant in healthy tissue from the HLCA core, specifically in venous endothelial cells (both pulmonary and systemic)." (PMID 37291214, 2023). "ACKR1 is expressed on the endothelial cells of tumour‐associated blood vessels." (PMID 35184398, 2022). "Compared to other EC subtypes,EC4 exhibited elevated expression levels of multiple genes implicated in antigen presentation (HLADRB1,HLA-DRB5,and HLA-DRA),immune cell recruitment (SELP,LIFR, and ACKR1),and anti-tumor inflammation (CCL14,IFITM1)." (PMID 41394809, 2025). "The CXCL - ACKR1/CCL - ACKR1 pairs potentially contributed to the enhanced immune response within the tumor." (PMID 40036264, 2025). "ACKR1 was exclusively expressed in the Tumor 1 cluster, suggesting a potentially pivotal role in regulating immune cell recruitment." (PMID 40036264, 2025). "The largest endothelial population, venous ECs, defined by the expression of the atypical chemokine receptor ACKR1, decreased in naïve tumor tissues compared to normal tissues and increased significantly following neoICT." (PMID 39334513, 2024). "During CXCL signaling, the atypical chemokine receptor 1 (ACKR1) mainly interacts with CXCL family members in tumor endothelial cells (TECs)." (PMID 38182557, 2024). "Meanwhile, we observed highly active lactate dehydrogenase in tumor cells, ACKR1+ endothelial cells, MKI67+ macrophages, CD8+ T cells, and vSMC cells." (PMID 37795453, 2023). "ACKR1 on tumor cells and erythrocytes inhibits angiogenesis by reducing the levels of pro-angiogenic chemokines." (PMID 37108425, 2023). "The direct interaction of ACKR1 on vascular endothelium with CD82/KAI1 on tumor cells leads to the inhibition of tumor cell proliferation and metastasis." (PMID 37108425, 2023). "Studies show that when ACKR1 is expressed on malignant cells it is protective against tumor angiogenesis and subsequent metastasis." (PMID 37006247, 2023). "Still, the mechanisms of ACKR1 retaining or sequestering different chemokines have yet to be elucidated in detail, particularly in the context of the tumor microenvironment." (PMID 37006247, 2023). "ACKR1+ tumour ECs showed that genes related to inflammatory response regulation were strongly up‐regulated, suggesting strong immune activation in the solid components." (PMID 35184398, 2022). "Compared with normal tissues and lesions with the GG radiological appearance, ACKR1+ tumour ECs were significantly enriched in lesions with the solid radiological appearance." (PMID 35184398, 2022).
tumor (continued). "ACKR1+ tumour endothelial cells, which up‐regulate genes related to inflammatory response regulation, were significantly enriched in the solid components." (PMID 35184398, 2022). "Endothelial cells from different sources were mixed and assigned to four cell types, including immune EDCs (CCL5 and CXCL13), lymphatic EDCs (PDPN and PROX1), tumor EDCs (ACKR1 and POSTN), and vascular EDCs (PLVAP and SLC9A3R2)." (PMID 34697289, 2021). "Cluster 5 (tumor core EC type III: Co3), were mainly derived from tumor core and were characterized by upregulation of immune-activated genes including IL1B, ACKR1, SELE, and VACM1, which are associated with inflammation and immune cell recruitment." (PMID 34228647, 2021). "In follicular epithelial cells from tumor samples, cytokine interactions were observed in ACKR1-positive endothelial cells." (PMID 34805166, 2021). "ACKR1 acts as a ‘‘decoy” for excess chemokine and has been suggested to limit tumor metastasis by dampening the pro-angiogenic environment." (PMID 30591657, 2018). "Nevertheless, in PCa, reduced ACRK1 expression on erythrocytes in men of African descent appeared not to be linked to aggressiveness while ACKR1-deficient mice showed increased tumor growth." (PMID 41258098, 2025). "While IGFBP3 was clearly expressed in TECs, we found that ACKR1 was instead expressed in a transitional subpopulation of ECs derived mainly from normal kidney tissue with a smaller contribution of ECs isolated from the tumor." (PMID 39516665, 2024). "On the other hand, some chemokine signaling-related molecules (such as CXCL10 and CXCL11) were associated with better patient OS, and these chemokines secreted by pEMT-like tumor cells may promote the recruitment of IgG1 PCs via ACKR1." (PMID 37138324, 2023). "We also observed that MDSC-secreted VEGFA and multiple chemokines CCL2, CXCL1, CXCL2, CXCL3, and CXCL8 could act on endothelial cells via VEGFA-KDR/FLT1 and CCL2/CXCLs-ACKR1 interactions, which were crucial for tumor angiogenesis." (PMID 37475874, 2023). "Testing ACKR1 genotype and expression in tumor biopsies may be a clinically useful cancer biomarker." (PMID 37006247, 2023). "Altering the global ACKR1 expression also changes the tumor microenvironment." (PMID 37006247, 2023). "Immunofluorescence staining showed that ACKR1 were highly expressed in tumor ECs." (PMID 35664061, 2022). "The upregulated differentially expressed protein-coding genes in subtype 2 include atypical chemokine receptor (ACKR1), which functions as a tumor suppressor in several cancers and plays an important role in transporting chemokines across cells to aid leukocyte transmigration." (PMID 35631431, 2022). "In contrast to KDR_EC, which promotes tumour progression, ACKR1_EC may inhibit tumour cell proliferation and reduce angiogenesis through ACKR1‐mediated tumour suppressive signalling pathways and by sequestering cytokines." (PMID 36305631, 2022). "Cellular interactions between tumor cells and endothelial, especially the CXCL1/ACKR1 and CXCL8/ACKR1 axes which may recruit ACKR1+ ECs, were enhanced in primary tumor tissues." (PMID 34185421, 2021). "It was suggested that by regulation of the excess of chemokines, especially CXCL8, ACKR1 may dampen the pro-angiogenic tumor microenvironment and limit tumor metastasis." (PMID 32456359, 2020). "Furthermore, ACKR1 protein expression was localized on normal brain and tumor microvascular cells, while CXCR1 and CXCR2 were present on tumor infiltrating leukocytes." (PMID 32456359, 2020). "On the contrary, ACKR1 was reducing tumor growth in a model of prostate cancer through the binding of angiogenic ELR+ CXC-chemokines that decreased angiogenesis and in a melanoma lung metastasis model, interacting with the tetraspanin CD82/KAI that induced tumor cells senescence." (PMID 30894861, 2019).
tumor (continued). "Indeed, overexpression of ACKR1 decreases tumor cellularity, vascularity and metastasis in different tumor mouse models, such as in breast cancer, where it significantly inhibits tumorigenesis and lung metastasis." (PMID 30591657, 2018). "Furthermore, it is possible ACKR1 could contribute cell cycle regulation through other interactions including the tumor suppressor CD82/KAI1, a multifunctional surface tetraspanin." (PMID 37006247, 2023). "Another enriched epithelial cluster is ACKR1+ ECs, which are involved in leukocyte cell–cell adhesion, leukocyte adhesion to vascular endothelial cell, and leukocyte migration, thus may reflect the lymphangiogenesis in tumor tissues." (PMID 34185421, 2021). "Substantiating this premise, EC4 subclass analysis identified conserved functional modules including ECM remodeling effectors (HSPG2,MGP,POSTN) and tumor niche-modifying factors (RAMP2,ACKR1,CD74)." (PMID 41394809, 2025). "Atypical chemokine receptor 1 (ACKR1), is known as a core regulator which binds chemokines involved in inflammatory responses and tumor proliferation, angiogenesis, and metastasis." (PMID 39440065, 2024). "RNA was extracted from tumor tissue, and the expression of DEIRGs including GREM2, CTSS, TINAGL1, ACKR1, HLA-DRB1, and STC2 was verified using real-time quantitative reverse transcription PCR (RT-qPCR)." (PMID 39735532, 2024). "By clearing these chemokines, ACKR1 can reduce their concentration in the TME, thereby decreasing the attraction and migration of tumour cells and inhibiting tumour growth and spread." (PMID 39601163, 2024). "We observed the expression level of LMRGs in different cell types, and we found that LDHA was mainly expressed in tumor cells and ACKR1+ endothelial, while LDHB was highly expressed in vSMC, tumor cells, mast cells, and CD8+ T cells." (PMID 37795453, 2023). "Ten chemokine receptors (CXCR1, CXCR2, CXCR4, CXCR6, CCR3, CCR6, ACKR4/CCRL1, CCLR2, CX3CR1, and ACKR1/DARC) were identified as differentially expressed from the DEG analysis between Black, White and Asian patient normal and tumor samples." (PMID 35754051, 2022). "The roles of ACKR1 and ACKR2 in tumor growth have also been evaluated in other cancer types where their expression has been correlated with a reduced tumor growth and survival benefit." (PMID 35008294, 2021). "Whereas, CXCR7/ACKR3 has predominantly pro-metastatic roles in cancer, ACKR1 and ACKR4 demonstrate mainly tumor-restricting effects." (PMID 32582148, 2020). "In contrast, ACKR1, ACKR4 and in many cases also ACKR2 exert anti-tumor functions at conventional migration-related processes as well as at non-conventional aspects." (PMID 32582148, 2020). "Protein-protein interaction analysis identified four hub genes-ASPN, SELE, ACKR1 and ABCB1-integrating ECM remodelling, endothelial-immune modulation and xenobiotic transport, reinforcing an immune-attenuated, metabolically adapted tumour landscape." (PMID 42194092, 2026). "Notably, tumor-specific intercellular signaling pathways, such as CSF1/CSF1R and CXCL/ACKR1, were identified, highlighting their potential role in fostering an immunosuppressive TME." (PMID 40438108, 2025). "For instance, tumor-infiltrating CD8+ T cells secreted CCL5,which bound to ACKR1 (atypical chemokine receptor 1)on EC5 cells.ACKR1,a scavenger receptor for inflammatory chemokines, may sequester CCL5 to attenuate T cell recruitment." (PMID 41394809, 2025). "ACKR1 on the surface of endothelial cells binds, clears and regulates various chemokines such as CXCL1, CXCL2, CCL13 and CCL18, which play key roles in angiogenesis and tumour progression." (PMID 39601163, 2024). "Therefore, ACKR1 has the potential to be a therapeutic target for treating various cancers, particularly if both ACKR1 and CXCR2 are expressed in tumor cells." (PMID 37108425, 2023).